BZW1 (basic leucine zipper and W2 domains 1)
Diseases named in the same sentence as BZW1 in open-access papers:
BZW1 is named in the same sentence as 25 diseases in open-access papers, as found by Europe PMC text mining. Sharing a sentence is not in itself a finding about the gene and the disease. The quoted sentences say what the papers report.
glioma (4 papers, 2021 to 2024). A benign or malignant brain and spinal cord tumor that arises from glial cells (astrocytes, oligodendrocytes, ependymal cells). "BZW1 expression is elevated in glioma tissue and increases with glioma WHO grade, reaching the highest levels in GBM." (PMID 38918274, 2024). "Potential diagnostic biomarkers MINK1, PLEKHM3, BZW1, and RCF2 had mRNA expression that differed significantly between GBM and the other glioma subtypes (p-values < 0.001)." (PMID 35877430, 2022). "The knockdown of NEAT1 resulted in significantly decreased proliferation of the U87 glioma cells compared with that of cells in the respective control group; the BZW1 overexpression rescued the change in si-NEAT1 expression, resulting in tumor reduction." (PMID 33393590, 2021). "Knockdown of NEAT1 was able to decrease the expression of BZW1 while up-regulating miR-98-5p, which can inhibit glioma progression in vivo." (PMID 33393590, 2021). "The results showed that BZW1 was up-regulated in glioma tissues compared with that in peritumor tissues." (PMID 33393590, 2021). "Taken these together, we found that silencing NEAT1 inhibited the proliferation of glioma cells by regulating the miR-98-5p/BZW1 axis." (PMID 33393590, 2021). "Taken together, these data suggest that the overexpression of BZW1 could rescue si-NEAT1-induced glioma cell tumorigenesis inhibition and that NEAT1’s oncogenic activity occurs partly via the miRNA-98-5p/BZW1 axis in glioma cells." (PMID 33393590, 2021). "We also identified that BZW1 was positively correlated with NEAT1 in glioma tissues." (PMID 33393590, 2021). "We validated the expression level of BZW1 in glioma tissues using real-time PCR." (PMID 33393590, 2021). "The inhibition of lncRNA NEAT1 or BZW1 might be an effective therapeutic strategy to treat glioma cancers." (PMID 33393590, 2021). "In summary, this may be the first discovery that the NEAT1/ miR-98-5p/BZW1 axis plays an important role in glioma." (PMID 33393590, 2021). "Next, a luciferase assay was performed to determine whether BZW1 was a direct target of miR-98-5p in glioma cells." (PMID 33393590, 2021). "NEAT1 may act as a competing endogenous lncRNA to up-regulate BZW1 by sponging hsa‐mir‐98‐5p in glioma." (PMID 33393590, 2021). "Our data suggest that NEAT1 could promote glioma tumorigenesis via the miR-98-5p/BZW1 axis in vivo." (PMID 33393590, 2021). "We hypothesized that BZW1 may be a direct target of miR-98-5p in glioma." (PMID 33393590, 2021). "The following Western blot assays showed that the relative protein level of BZW1 in the U87 and U251 cells was significantly decreased after transfection with miR-98-5p, while blockage of miR-98-5p could increase the BZW1 expression level in glioma cells." (PMID 33393590, 2021). "Targeting NEAT1/miR-98-5p/BZW1 may be a novel therapeutic treatment approach for glioma patients." (PMID 33393590, 2021). "In order to validate the role of BZW1 in NEAT1/miR-98 axis in glioma, NEAT1-siRNA and BZW1 vector were transfected and the transfection efficiency was measured in the U87." (PMID 33393590, 2021). "In glioma, the lncRNA NEAT1 promotes tumour progression by regulating the miR‐98‐5p/BZW1 axis." (PMID 39462268, 2024).
lung carcinoma (3 papers, 2019 to 2026). "Overexpression of BZW1 in lung cancer cells revealed a novel pathway underlying the induction of lung cancer metastasis." (PMID 31601833, 2019). "The heat map clearly showed that high BZW1 expression was associated with recurrence events in lung cancer patients." (PMID 31601833, 2019). "BZW1 expression is associated with the EGFR mutant type in lung cancer, and knockdown of BZW1 expression significantly decreases the cellular migration ability in vitro." (PMID 31601833, 2019). "Notably, BZW1 mutations were most prevalent in bone cancer, ovarian, colorectal and lung cancers, hinting at a potential association between BZW1 mutations and specific cancer types." (PMID 39462268, 2024). "Therefore, we proposed that BZW1 may be associated with lung cancer tumorigenesis or metastasis events." (PMID 31601833, 2019). "Next, we validated these findings by IHC staining for the BZW1 protein in clinical lung cancer tissues." (PMID 31601833, 2019). "The knockdown of BZW1 by its specific shRNA significantly mediated the invasive/migratory capabilities of the metastatic lung cancer cell line CL1-5." (PMID 31601833, 2019). "BZW1 had especially significant p-values in lung cancer as determined via either microarray (Lung Meta-base, 6 cohorts, n = 1053, HR = 1.39), RNA-seq (The Cancer Genome Atlas, TCGA, n = 475, HR = 1.41), or both." (PMID 31601833, 2019). "Due to our data indicates BZW1 had closely correlation between expression levels with metastatic ability in lung cancer cells." (PMID 31601833, 2019). "To evaluate the clinical pertinence of BZW1 in lung cancer patients, we analyzed the microarray database GSE31210." (PMID 31601833, 2019). "To confirm the prognostic significance of BZW1 in lung cancer, we analyzed the hazard ratio and Cox-p value in microarray datasets from the Prognoscan website." (PMID 31601833, 2019). "We investigated the correlation of BZW1 with tissue invasion and metastasis in a cell line model and clinical events of lung cancer." (PMID 31601833, 2019). "Merging the evidence, we noted a positive correlation between endogenous BZW1 expression and cellular invasive/migratory activity in various lung cancer cell lines." (PMID 31601833, 2019). "We are recruiting more patients and establishing a validation cohort to verify BZW1 as a prognostic marker in lung cancer." (PMID 31601833, 2019). "In our data, we provided evidence that BZW1 expression levels correlated with recurrence events in a lung cancer cohort." (PMID 31601833, 2019). "BZW1, as a novel cancer gene, may play a crucial role in the treatment of lung cancer when targeted with specific inhibitors." (PMID 39462268, 2024). "Moreover, the BZW1 levels in tumors obtained from clinical lung cancer cohorts were significantly higher than the levels in the adjacent normal tissues from GSE7670." (PMID 31601833, 2019). "To confirm whether BZW1 indeed affected metastatic events in lung cancer, we detected the endogenous expression of BZW1 in lung cancer cell panels." (PMID 31601833, 2019). "The univariate results revealed several clinicopathological parameters, including the BZW1 expression level and N/M status, that could be used for prognostic factors for patients with lung cancer." (PMID 31601833, 2019). "Therefore, we chose to further investigate the role of BZW1 in lung cancer." (PMID 31601833, 2019). "Thus, BZW1 has the potential to be an independent lung cancer prognostic factor." (PMID 31601833, 2019). "Furthermore, knockdown of BZW1 expression inhibited the migration abilities of lung cancer cells." (PMID 31601833, 2019). "We found that BZW1 expression is an independent prognostic factor and has great prognostic significance for both OS and DFS in lung cancer patients." (PMID 31601833, 2019). "Combining all evidence, we established a relationship between BZW1 and EGFR in lung cancer metastasis." (PMID 31601833, 2019).
lung carcinoma (continued). "Therefore, we integrated the mRNA levels of BZW1 and EGFR with the survival curves of online lung cancer databases." (PMID 31601833, 2019). "Our findings establish BZW1 as a ferroptosis suppressor whose inhibition may synergize with immunotherapy in LUAD, highlighting the therapeutic potential of targeting the BZW1-ferroptosis axis for lung cancer treatment." (PMID 41833002, 2026). "Hence, we observed that BZW1 and its binding molecule DCTN show similar trends in lung cancer." (PMID 31601833, 2019). "BZW1 was plenteously expressed in metastatic lung cancer cell lines, e.g., CL1-5, but its expression was relatively lower in nonmetastatic lung cancer cell lines, e.g., CL1-0 and H928." (PMID 31601833, 2019).
ovarian carcinoma (3 papers, 2022 to 2025). A malignant neoplasm originating from the surface ovarian epithelium. "Additionally, miR-129-3p negatively regulated Basic leucine zipper and W2 domains 1 (BZW1) functioned as cell cycle regulator, resulting in reduced cell proliferation in colorectal and ovarian cancer." (PMID 39851970, 2025). "MiR-129-3p serves as a tumor suppressor by targeting BZW1 in ovarian cancer cells and the restoration of miR-129-3p might be a novel therapeutic strategy for ovarian cancer." (PMID 35492611, 2022).
endometriosis (2 papers, 2018 to 2022). The growth of functional endometrial tissue in anatomic sites outside the uterine body. "In addition, the transcriptional regulator BZW1 (basic leucine zipper and W2 domains 1) gene located within SCR25 has been linked to bovine endometriosis." (PMID 29566643, 2018).
lung adenocarcinoma (2 papers, 2019 to 2024). A carcinoma that arises from the lung and is characterized by the presence of malignant glandular epithelial cells. "Exploring the role of novel cancer gene BZW1 in lung adenocarcinoma (LUAD) and unveiling associated signalling pathways." (PMID 39462268, 2024). "Further, high BZW1 expression predicts poor prognosis better in lung adenocarcinoma subtype patients than in squamous subtype carcinoma patients." (PMID 31601833, 2019). "Developing inhibitors for BZW1 PPIs may be a potential therapeutic strategy for lung adenocarcinoma." (PMID 31601833, 2019). "However, little is known about the role of BZW1 in lung adenocarcinoma (LUAD)." (PMID 39462268, 2024). "By searching public databases, we found that high BZW1 expression was significantly correlated with poor survival rate in non-small cell lung cancer (NSCLC), especially in lung adenocarcinoma." (PMID 31601833, 2019). "In summary, BZW1 expression serves as an independent prognostic factor of NSCLC, especially in lung adenocarcinoma." (PMID 31601833, 2019). "The results revealed that BZW1 had a strong correlation with survival time in lung adenocarcinoma patients but not in patients with the squamous cell carcinoma subtype." (PMID 31601833, 2019).
pancreatic cancer (2 papers, 2023 to 2024). "High BZW1 expression is associated with poor prognosis in pancreatic cancer, and BZW1 expression positively correlates with infiltration of the tumor microenvironment (TME) by CD8+ T cells, macrophages, and neutrophils." (PMID 38918274, 2024). "Basic leucine zipper and W2 domain-containing protein 1 (BZW1) promotes tumor growth by facilitating aerobic glycolysis and serves as a therapeutic target for pancreatic cancer patients." (PMID 36830013, 2023).
pancreatic ductal adenocarcinoma (2 papers, 2024 to 2025). An infiltrating adenocarcinoma that arises from the epithelial cells of the pancreas. "successfully demonstrated that BZW1 can promote glycolysis in pancreatic ductal adenocarcinoma by enhancing eIF2α, consistent with our single‐cell sequencing analysis showing that BZW1 affects metabolism and thus tumour growth outcomes." (PMID 39462268, 2024). "In recent years, BZW1 has been identified as enhancing phosphorylation to promote glycolysis in pancreatic ductal adenocarcinoma." (PMID 39462268, 2024). "In pancreatic ductal adenocarcinoma (PDAC), overexpression of the basic leucine zipper and W2 domains 1 (BZW1) protein functions as an adaptor for PERK, promoting the phosphorylation of eIF2α." (PMID 41209558, 2025).
Alzheimer disease (1 paper, 2022). A progressive, neurodegenerative disease characterized by loss of function and death of nerve cells in several areas of the brain leading to loss of cognitive function such as memory and language. "The roles of BZW1 in tumor growth and Alzheimer’s disease progression have also been well demonstrated." (PMID 35565529, 2022).
colon cancer (1 paper, 2019). "BZW1 was overexpressed in several cancer types and was associated with high hazard ratios in lung, pancreatic and colon cancer." (PMID 31601833, 2019).
glioblastoma (1 paper, 2025). The most malignant astrocytic tumor (WHO grade IV). "The lncRNA-NEAT1/miR-98-5p/BZW1 axis plays an important role in glioblastoma, so targeted therapies to this axis can be explored." (PMID 40110044, 2025).
prostate carcinoma (1 paper, 2022). A carcinoma that arises from epithelial cells of the prostate gland. "Some studies have reported that BZW1 is highly expressed in cancer tissues and cell lines such as prostate cancer and lung adenocarcinoma." (PMID 36333315, 2022).
renal clear cell carcinoma (1 paper, 2024). "Additionally, we employed the UALCAN database for online analysis of BZW1 protein expression in BRCA, renal clear cell carcinoma and LUAD." (PMID 39462268, 2024).
tumor (9 papers, 2021 to 2024). "To corroborate our conclusions, we performed an analysis of tumour‐related immune processes using single‐cell data from CancerSEA, revealing close associations between BZW1 and EMT." (PMID 39462268, 2024). "To further validate this phenomenon, we delved into single‐cell data from the CancerSEA database, revealing a close association between BZW1 and the tumour‐related process of EMT." (PMID 39462268, 2024). "Given the impact of genetic alterations on tumour progression, we further scrutinized the mutational landscape of BZW1 across diverse cancer types." (PMID 39462268, 2024). "Moreover, we found that BZW1 is associated with tumour cell behaviours, including cell invasion, cell cycle and tumour metabolism." (PMID 39462268, 2024). "To further illustrate that BZW1 can influence tumour cell EMT through the Wnt/β‐catenin pathway, we conducted additional experiments using the Wnt/β‐catenin pathway activator LiCl." (PMID 39462268, 2024). "Our analysis of cell annotation results revealed a significant elevation of BZW1 expression in malignant tumour cells, consistent with our prior findings." (PMID 39462268, 2024). "Our research similarly demonstrates that BZW1 can influence tumour cell proliferation by modulating the Wnt/β‐catenin signalling pathway, consistent with previous studies." (PMID 39462268, 2024). "To validate the reliability of the screened tumour‐related functions of BZW1 in the bioinformatics database, we conducted subsequent experiments using two commonly used LUAD cell lines, A549 and H1299." (PMID 39462268, 2024). "In summary, our analysis suggests that elevated expression of BZW1 promotes EMT in tumour cells, thereby enhancing their invasion and migration capabilities." (PMID 39462268, 2024). "To further explore the role of BZW1 in tumour progression, we conducted stage‐specific expression analyses focusing on cancers with significant expression differences between tumour and normal groups." (PMID 39462268, 2024). "Utilizing extensive single‐cell sequencing data analysis, we delineated the potential impact of BZW1 on various tumour‐related processes." (PMID 39462268, 2024). "BZW1 and BZW2 expression are positively associated with T cell mediated immune response to tumor cell and Th2 cells in PAAD." (PMID 36267402, 2022). "The PAAD_CRA001160 cohort in the TISCH database was used to investigate the relationships between BZW1/2 expression levels and tumor stromal cell infiltrations." (PMID 36267402, 2022). "Tumor Immune Single-Cell Hub (TISCH) analyses indicated that BZW1 and BZW2 were mainly expressed in B cells and malignant cells." (PMID 36267402, 2022). "A significant expression difference of BZW1 between normal and tumor samples was observed in 28 species." (PMID 36267402, 2022). "BZW1 and BZW2 expression were positively associated with T cell mediated immune response to tumor cell and Th2 cells in xCell database." (PMID 36267402, 2022). "Furthermore, experimental validation underscored BZW1's capacity to influence tumour EMT through modulation of the Wnt/β‐catenin pathway." (PMID 39462268, 2024). "Furthermore, BZW1 has been shown to influence tumour cell development by affecting various signalling pathways." (PMID 39462268, 2024). "However, our research indicates that reducing BZW1 levels promotes tumour cell apoptosis, contradicting database results." (PMID 39462268, 2024). "Therefore, we still believe that reducing BZW1 promotes tumour cell apoptosis." (PMID 39462268, 2024). "Therefore, high expression of BZW1 promotes the invasive activity of tumour cells." (PMID 39462268, 2024). "To elucidate the specific mechanisms by which BZW1 promotes EMT, we conducted additional investigations and found that BZW1 can induce EMT in tumour cells through the Wnt/β‐catenin pathway." (PMID 39462268, 2024).
tumor (continued). "In addition, the results of correlation analysis suggested that BZW1 and BZW2 expression was negatively associated with neutrophil activation involved in the immune response but positively correlated with T cell mediated immune response to tumor cells (Ps < 0.05)." (PMID 36267402, 2022). "BZW1 and RCF2 displayed the opposite trends; their expression was significantly upregulated in GBM compared to non-tumor (p-values < 0.001)." (PMID 35877430, 2022).
cancer (8 papers, 2014 to 2024). A tumor composed of atypical neoplastic, often pleomorphic cells that invade other tissues. "Thus, our study provides insights into BZW1‐associated immune cell dynamics and its relevance to cancer immunotherapy." (PMID 39462268, 2024). "Our study initially employed bioinformatics approaches to identify a trend of high expression of BZW1 in various cancer cells." (PMID 39462268, 2024). "We initially utilized the Timer2.0 database and GEO data to analyse the expression pattern of BZW1 across 33 cancer types, revealing predominantly high expression levels in most cancers." (PMID 39462268, 2024). "Utilizing various databases, we conducted a pan‐cancer analysis of BZW1 and observed its overexpression across multiple cancer types." (PMID 39462268, 2024). "In recent years, the discovery of BZW1 as a novel cancer gene holds significant scientific significance." (PMID 39462268, 2024). "The results showed that BZW1 plays a significant role in cancers of the lung, pancreas, colon, head and neck, and prostate; as such, its potential clinical value and involved molecular mechanisms still need to be further investigated." (PMID 31601833, 2019). "As a recently discovered cancer gene, BZW1 has been the subject of limited research." (PMID 39462268, 2024). "In this article, we systematically analysed the role of BZW1 in cancer." (PMID 39462268, 2024). "Our research firstly demonstrated the elevated expression of BZW1 in various cancer cells." (PMID 39462268, 2024). "There are few reports have reported that BZW1 is involved in cancer." (PMID 33393590, 2021). "However, details about the mechanism by which BZW1 regulates EGFR activity in cancer still needs further investigation." (PMID 31601833, 2019). "Based on previous researches, miR-98-5p is available to regulate cancer development through various target genes, like XIAP, BZW1, STAT3, IGF1 and so on." (PMID 34895048, 2021). "To identify the roles of the expression of BZW family members (BZW1 and BZW2) in cancer patients, we screened comprehensive datasets and found the corresponding hazard ratios and p-values from in silico analysis." (PMID 31601833, 2019).
BZW1 also shares sentences with these, for which no sentence is quoted: endometritis (2 papers); squamous carcinoma (2); bone cancer (1); female infertility (1); immune complex diseases (1); lupus (1); myopia (1); non-small cell lung carcinoma (1); pancreatic adenocarcinoma (1); rheumatoid arthritis (1); Sepsis (1).